CYBC1 (cytochrome b-245 chaperone 1)
Description:
Functions as a chaperone necessary for a stable expression of the CYBA and CYBB subunits of the cytochrome b-245 heterodimer. Controls the phagocyte respiratory burst and is essential for innate immunity (By similarity).
Synonyms: Eros; C17orf62; MGC4368; FLJ90469; CGD5
Tractability: Small molecule: a structure with a bound ligand is known. Antibody: UniProt predicts a signal peptide or a membrane-spanning region. PROTAC: ubiquitination databases record sites on it.
Gene: Protein-coding gene on chromosome 17 (82,440,912 to 82,450,829, reverse strand). Ensembl gene ENSG00000178927.
Subcellular location: Endoplasmic reticulum membrane
Subcellular location (Human Protein Atlas): Plasma membrane; Cell Junctions
Gene Ontology:
Molecular function: protein binding
Biological process: innate immune response; respiratory burst after phagocytosis
Cellular component: endoplasmic reticulum; endoplasmic reticulum membrane
Genetic constraint (gnomAD): Loss-of-function variants: 23 observed, 20.9 expected, observed/expected ratio (o/e) 1.1, 90% interval 0.79 to 1.56. The upper end of that interval is the gene's LOEUF score, 1.56, which puts it in group 6 of 6, group 1 being the genes least tolerant of losing a copy. Missense variants: 237 observed, 231.79 expected, observed/expected ratio (o/e) 1.02, 90% interval 0.92 to 1.14. Synonymous variants: 112 observed, 93.55 expected, observed/expected ratio (o/e) 1.2, 90% interval 1.03 to 1.4.
Homologues: Orthologues: macaque CYBC1 (91% identical), dog CYBC1 (89% identical), guinea pig CYBC1 (89% identical), rat Cybc1 (89% identical), mouse Cybc1 (89% identical), chimpanzee CYBC1 (80% identical), pig CYBC1 (75% identical), rabbit CYBC1 (73% identical), tropical clawed frog cybc1 (66% identical), zebrafish cybc1 (60% identical).
Diseases named in the same sentence as CYBC1 in open-access papers:
CYBC1 is named in the same sentence as 10 diseases in open-access papers, as found by Europe PMC text mining. Sharing a sentence is not in itself a finding about the gene and the disease. The quoted sentences say what the papers report.
chronic granulomatous disease (8 papers, 2018 to 2025). Chronic granulomatous disease (CGD) is a rare primary immunodeficiency, mainly affecting phagocytes, which is characterized by an increased susceptibility to severe and recurrent bacterial and fungal infections, along with the development of granulomas. "Chronic granulomatous Disease (CGD) is a rare innate immunodeficiency disorder caused by mutations in one of the six genes (CYBA, CYBB, NCF1, NCF2, NCF4, and CYBC1/EROS) encoding the superoxide-producing nicotinamide adenine dinucleotide phosphate (NADPH)—oxidase complex in phagocytes." (PMID 33746979, 2021).
colitis (1 paper, 2018). Inflammation of the colon. "Overall, we find that CYBC1 deficiency results in CGD characterized by colitis and a distinct profile of infections indicative of macrophage dysfunction." (PMID 30361506, 2018). "An excess of colitis in the group of homozygotes, as well as a distinct profile of infections, suggests that CYBC1 deficiency has a more pronounced effect on macrophages." (PMID 30361506, 2018). "To investigate the consequences of CYBC1 p.Tyr2Ter, we searched for pathological manifestations in these six additional homozygotes and found that three had colitis, like the two probands, and had received a diagnosis of inflammatory bowel disease (IBD)." (PMID 30361506, 2018).
liver cancer (1 paper, 2024). An epithelial or non-epithelial malignant neoplasm that arises from the liver. "In chronic inflammation caused by HCC, dysregulated ROS production, which CYBC1 may affect, may lead to a pro-inflammatory environment and promote the development of liver cancer." (PMID 39055701, 2024). "The expression differences of the six Hub genes C3, CTNNB1, CYBC1, DNASE1L3, IRAK1, and SERPINE1 between human liver cancer cell lines and normal liver cell lines are statistically significant." (PMID 39055701, 2024). "The cell lines showed relatively low expression compared with normal liver cells, while CTNNB1, CYBC1, IRAK1, and SERPINE1 showed relatively high expression in HCCLM3 and 97H liver cancer cell lines compared with normal liver cells." (PMID 39055701, 2024). "Among the six hub genes, C3 and DNASE1L3 are relatively low expressed in HCCLM3 and 97H liver cancer cell lines, while CTNNB1, CYBC1, IRAK1, and SERPINE1 are relatively overexpressed in liver cancer cell lines." (PMID 39055701, 2024).
cancer (1 paper, 2024). A tumor composed of atypical neoplastic, often pleomorphic cells that invade other tissues. "The CYBC1-cytochrome b-245 complex is essential for producing ROS, and NADPH oxidase and its ROS can affect cancer’s development and progression." (PMID 39055701, 2024).
tumor (1 paper, 2024). "Alterations in CYBC1 expression or function may affect the immune system’s ability to respond to tumor cells." (PMID 39055701, 2024). "The mRNA expression of six inflammation-related genes (C3, CTNNB1, CYBC1, DNASE1L3, IRAK1, and SERPINE1) is closely related to the overall survival rate, tumor immune infiltration, and clinical stage of HCC patients." (PMID 39055701, 2024).
CYBC1 also shares sentences with these, for which no sentence is quoted: infection (3 papers); bacterial infection (1); hepatocellular carcinoma (1); inflammatory bowel disease (1); influenza (1).